CCDC125 (coiled-coil domain containing 125)
Description:
May be involved in the regulation of cell migration.
Synonyms: KENAE
Tractability: PROTAC: ubiquitination databases record sites on it.
Gene: Protein-coding gene on chromosome 5 (69,280,175 to 69,332,809, reverse strand). Ensembl gene ENSG00000183323.
Subcellular location: Cytoplasm
Subcellular location (Human Protein Atlas): Intermediate filaments; Nuclear membrane; Nucleoplasm
Gene Ontology:
Molecular function: identical protein binding; protein binding
Biological process: activation of GTPase activity; negative regulation of cell motility; negative regulation of Rho protein signal transduction; regulation of cell motility
Cellular component: cytoplasm
Genetic constraint (gnomAD): Loss-of-function variants: 22 observed, 32.38 expected, observed/expected ratio (o/e) 0.68, 90% interval 0.48 to 0.97. The upper end of that interval is the gene's LOEUF score, 0.97, which puts it in group 4 of 6, group 1 being the genes least tolerant of losing a copy. Missense variants: 432 observed, 467.17 expected, observed/expected ratio (o/e) 0.92, 90% interval 0.85 to 1. Synonymous variants: 135 observed, 155.03 expected, observed/expected ratio (o/e) 0.87, 90% interval 0.76 to 1.
Homologues: Orthologues: chimpanzee CCDC125 (99% identical), macaque TAF9 (95% identical), rabbit CCDC125 (76% identical), dog CCDC125 (75% identical), pig CCDC125 (74% identical), mouse Ccdc125 (72% identical), guinea pig CCDC125 (71% identical), rat Ccdc125 (70% identical), tropical clawed frog ccdc125 (46% identical).
Diseases named in the same sentence as CCDC125 in open-access papers:
CCDC125 is named in the same sentence as 4 diseases in open-access papers, as found by Europe PMC text mining. Sharing a sentence is not in itself a finding about the gene and the disease. The quoted sentences say what the papers report.
neuroblastoma (1 paper, 2024). Neuroblastoma (NB) is the most common solid, extracranial childhood tumor. "Together these findings suggest that CCDC125 may be a potential target for further neurophysiology studies and could be implicated in early neurodevelopment and neuroblastoma." (PMID 38398114, 2024). "The role of CCDC125 in neuroblastoma remains uncharacterised, but its upregulation is a good prognostic biomarker for gastric and thyroid cancers, which contrasts to our prediction in neuroblastoma, suggesting possible tissue-specificity." (PMID 38398114, 2024). "The upregulation of genes BSG/CD147, CCDC125, GABRB3, GNB2L1/RACK1, HAPLN4, HEBP2, and HSD17B12 is associated with poor neuroblastoma prognosis and low EFS." (PMID 38398114, 2024).
CCDC125 also shares sentences with these, for which no sentence is quoted: cancer (1 paper); prostate carcinoma (1); thyroid cancer (1).